ATG7 (autophagy related 7)
Diseases named in the same sentence as ATG7 in open-access papers (continued):
Sharing a sentence is not in itself a finding about the gene and the disease.
tumor (continued). "We chose to perform RNA sequencing on tumor tissues obtained from Atg7ΔHep and Atg7/Hmgb1ΔHep mice at the age of 15-months old, when the tumor number and size were comparable in these mice." (PMID 32382012, 2020). "Next, we confirmed that apatinib affected the ATG7 mRNA levels in the tumor tissues of BGC-823 cell-mediated xenografts and in GC cell lines." (PMID 32139670, 2020). "Further supporting this notion, we found that the expression of Cyclin D1 was more significantly upregulated in the tumor of Atg7ΔHep liver than in the tumors of the Atg7/Hmgb1ΔHep livers." (PMID 32382012, 2020). "PCA thus suggests that tumors from the two strains of mice were quite different with those from Atg7/Hmgb1ΔHep livers more similar to the non-tumor tissues in their transcriptomic profiles." (PMID 32382012, 2020). "While treatment with anti–PD-1 + HCQ significantly suppressed tumor growth rates compared with monotherapy in B16 Atg7 WT cells, no such augmentation of anti–PD-1 efficacy was observed in B16 Atg7-KO tumors treated with anti–PD-1." (PMID 32780726, 2020). "Blocking autophagy by liver-specific deletion of the important autophagy genes Atg7 and Atg5, which generated circulating arginase I and inhibited tumor growth and identifies a metabolic vulnerability of cancer." (PMID 33510635, 2020). "Previous findings suggest that Atg7 depletion leads to enhanced MHC class I presentation in tumor cells but reduced MHC class II expression." (PMID 32780726, 2020). "ATG5 and ATG7 have previously been reported to be the mutual targets of different lncRNAs for regulating autophagy in several tumor cells." (PMID 33230459, 2020). "In this study, despite displaying reduced tumor growth, HRasV12 expressing atg5−/− or atg7−/− tumors had increased EMT marker expression, which was reverted using a NF-κB inhibitor." (PMID 31554173, 2019). "Similar results have been observed in mice with systemic mosaic Atg5 deletion or liver-specific deletion of Atg7, which led to the development of benign liver adenomas." (PMID 31554173, 2019). "Conversely, when autophagy is lost in regulatory T-cells by disrupting Atg7, there was impaired ability of the anti-tumor immune response to CRC cells." (PMID 31671556, 2019). "The results consistently demonstrate that ATG7 mediates BC cell autophagy, which is also crucial for BC invasion and tumor growth, as demonstrated by the inhibition of BC autophagy." (PMID 31016112, 2019). "Our studies present very strong evidence indicating that ATG7‐dependent autophagy acts as a tumor positive regulator for BC invasion and growth." (PMID 31016112, 2019). "Conversely, ATG7 deficiency prevents the tumor initiation and progression induced by APC loss via the activation of specific anti-tumor T response and microbiota imbalance." (PMID 30871055, 2019). "As a pivotal regulator in autophagy initiation and autophagosome formation, ATG7 contributes to tumor cell proliferation, cell death and drug resistance." (PMID 29311760, 2018). "Despite decreased tumor burden, mice with Atg7-null tumors died from pneumonia with an increased inflammatory response." (PMID 30622432, 2018). "Of note, an essential role for autophagy in PDAC growth and survival has recently emerged, and the autophagy essential gene Atg7 has been shown to fuel tumor growth in mice containing oncogenic Kras (the most common mutation event in human PDACs)." (PMID 29410677, 2018). "In the present study, we found that miR-20a-5p was downregulated while ATG7 was upregulated in NB tumor specimens." (PMID 29311760, 2018).
tumor (continued). "The myeloid cell-specific deletion of Atg7 also manifest the decreased lung metastasis of B16 tumors, implying that myeloid cell-specific autophagy promotes tumor metastasis in general." (PMID 28686632, 2017). "HSF-1 upregulated Atg7 expression by directly binding to the ATG7 promoter which, in turn, activated autophagy and promoted tumor cell resistance." (PMID 28978341, 2017). "Our further results showed that the expression of IL-6, a prominent proangiogenic factor involved in angiogenesis during tumor progression, was significantly decreased in Atg7-silenced HBMEC compared to the control." (PMID 28467355, 2017). "On the other hand, positive regulatory effects of ATG7 on tumor growth and invasion have also been reported." (PMID 28624205, 2017). "All of these studies strongly reveal that the specific biological effects of ATG7 on tumor growth and progression are tumor type-dependent." (PMID 28624205, 2017). "A standard IHC with anti-ATG7 antibody staining was performed on the xenograft tumor collected at days 3, 7, and 14 after treatment with or without doxycycline." (PMID 27247826, 2016). "Cytosolic FoxO1 can bind to Atg7 to induce autophagy in human tumour cells independently of its transcriptional activity." (PMID 27010363, 2016). "Taken together, these results suggest that NASTRp suppresses the tumor-promoting role of autophagy through ATG7 down-regulation and p62 accumulation, induces ER stress with activation of UPR, and eventually leads to cell death in human NSCLC cells." (PMID 25897662, 2015). "Two main hallmarks of cancer cells are unrestricted proliferation and suppressed cell death, raising the possibility of ATG7 as both an oncogene and a tumor suppressor." (PMID 26404030, 2015). "Further results showed that combined treatment of bortezomib and 3-MA or siRNA knockdown of Atg7 resulted in a marked increase in caspase 3 activation compared with the tumor cells that were treated with bortezomib alone." (PMID 24104452, 2014). "Notably, this study represents the first global exploration of BCc1 nanomedicine's potential to induce autophagy, a process mediated by autophagy-related genes (Beclin-1, ATG-4B, ATG-7, and mTOR), while evaluating tumor cell death." (PMID 41550506, 2026). "Given the critical role of autophagic regulation in controlling tumor immune evasion and cell death, the present study investigates the effects of BCc1 on key autophagy-associated genes ATG-4B, ATG-7, Beclin-1 and the mTOR signaling pathway using a BALB/c mouse model of BC." (PMID 41550506, 2026). "Additionally, CSF2 upregulated PD-L1 expression in tumor cells and activated autophagy by increasing LC-3, Beclin1, and ATG7 levels." (PMID 41216204, 2025). "The activation of autophagy-related genes, such as ATG5 and ATG7, facilitates the shift from tumor suppression to cytoprotective autophagy and hence, alteration in expression of these gene may improve the effectiveness of chemotherapeutic agents." (PMID 40176914, 2025). "We further validated our findings using Atg7#2 silenced tumor cells." (PMID 40611330, 2025). "To investigate the role of blocking endothelial autophagy in tumor vasculature and immune microenvironment optimization, we utilized endothelial cell-specific Atg7 conditional knockout (Atg7iECKO) mice generated by crossing VE-Cadherin-Cre-ERT2 transgenic mice with Atg7-floxed mice." (PMID 39744218, 2025). "Emerging evidence underscores the dual role of ATG7 as both an oncogene and a tumor suppressor, orchestrating a multifaceted impact on cellular processes encompassing cell proliferation, survival, traffic, protein secretion, signaling transduction, and cancer treatment." (PMID 40707430, 2025). "In co-cultures of T47DPar CLuc+ with either T47DATG7 FLuc+-GLuc+ (Test-Suspension) or T47DPar FLuc+-GLuc+ cells (Control-Suspension), the ATG7-knockout tumor cells were progressively depleted by DCA and Metformin, confirming their metabolic vulnerability in a competitive setting in vitro." (PMID 40113784, 2025).
tumor (continued). "ATG7 may also serve as a tumor suppressor in the TME and thus become a new candidate for diagnosis and prognosis." (PMID 40707430, 2025). "Thus, we induced Atg7 knockout with tamoxifen post-tumor transplantation, and our results demonstrated that suppressing endothelial cell autophagy after vascular network formation promoted improved vascular architecture and function." (PMID 39744218, 2025). "In non-small cell lung cancer, ATG7 can activate autophagy and thus inhibit tumor growth." (PMID 40231206, 2025). "OPN overexpression could promote GPX4 level and decrease autophagy-related LC3II/I, Atg5 and Atg7 expressions in tumor cells, which was subsequently reversed by LY294002 administration." (PMID 38526702, 2024). "Subsequently, we investigated whether CD8+ T cells regulate ATG7-mediated anti-tumor immune response." (PMID 38627815, 2024). "Moreover, we determined the expression of NCX1, CD138, Ki67, ATG5 and ATG7 in tumor sections by immunohistochemical staining." (PMID 38711131, 2024). "In addition, we identified HMGCR as a key gene involved in cholesterol metabolism and contributing to the anti-tumor effects of ATG7 inhibition." (PMID 38627815, 2024). "Considering that CD8+ T cell-dependent metabolic remodeling, facilitated by ATG7 inhibition, improves the efficacy of anti-tumor immunity, we investigated whether targeting ATG7 could further improve anti-tumor efficacy of PD-1 blockade." (PMID 38627815, 2024). "Studies have demonstrated that ATG5 and ATG7 regulate ferroptosis-mediated tumor IT." (PMID 39281375, 2024). "However, subcutaneous inoculation of Atg5‐overexpressed Atg7−/− MEF cells into NOD/SCID mice induced temporary tumor formation in the early stage of tumor formation." (PMID 38826147, 2024). "Altered ATG7 expression levels correlate with tumor progression and prognostic outcomes in TNBC166." (PMID 38553562, 2024). "Furthermore, we employed adipocyte-specific Atg7 KO mice (ATG7aKO) to assess the tumor progression of MC-38 and EO771." (PMID 38744820, 2024). "IHC staining was performed to test ATG7 expression in tumor tissues from nude mice." (PMID 38851811, 2024). "Loss of ATG7 produces the opposite result, promoting EMT in tumor cells." (PMID 38553562, 2024). "Another example of autophagic tumor suppression is Autophagy Related 7 (ATG7)." (PMID 38612567, 2024). "In KrasG12D-driven NSCLC, loss of autophagy via Atg7 deletion before lung tumor onset did not affect tumor growth, while blocked tumor progression in mice with preexisting lung cancer." (PMID 36675307, 2023). "Our results indicated that high level of lnc‐FSD2‐31:1 in tumor cells suppressed tumor growth, and suppression of ATG7 in CAFs could rescue these effects." (PMID 36727832, 2023). "Interestingly, it has been indicated that ATG5 or ATG7 deletion in T cells produces severe tumor implant rejection in the syngeneic mouse tumor model." (PMID 36160153, 2022). "We first investigated whether BECN1, LC3, and ATG10 are essential for maintaining tumor cell proliferation under metabolic stress, similar to what has been reported for ATG7." (PMID 35681458, 2022). "The genetic loss of Atg5 and Atg7 increased the levels of SQSTM1/p62, oxidative stress, mitochondrial swelling, and genomic damage observed in the primary hepatocytes, and the deletion of the p62 gene reduced the tumor size in Atg7 deficient hepatic tumors." (PMID 35252196, 2022). "Besides that, specific deletion of two essential genes, ATG7 or ATG5, in Treg cells impaired their survival fitness and lineage stability, leading to loss of Treg and greater tumor resistance." (PMID 35600411, 2022).
tumor (continued). "Beclin-1, Atg4, Atg5, and Atg7 have indicated a tumor-suppressive function." (PMID 34122670, 2021). "Deletion of autophagic genes such as FIP200 or ATG5 or ATG7 abolishes tumor growth in mouse models." (PMID 34944772, 2021). "Initially, it was thought that autophagy is required for progression of liver tumours to malignancy, as Atg7 KO caused adenoma formation but no cancerous tumours were detected." (PMID 34725936, 2021). "This may facilitate a deeper understanding of the role of ATG7 in these cancers—whether they underpin tumour growth or play a supportive role in the later stages of disease." (PMID 34725936, 2021). "However, it has also been reported that there is deletion of the autophagy related genes ATG3 and ATG7 in RAS-driven early stage tumor mouse models." (PMID 34823534, 2021). "Also, as compared to ATG5 and ATG7, Beclin1-dependent and Beclin1-independent properties play an important role during embryonic development and tumor suppression." (PMID 33628386, 2021). "Further, we show that Atg7-deficiency in microglia did not impact on their ability to respond to alternative stimulus, such as one driving them towards an anti-inflammatory/tumor supportive phenotype." (PMID 34082793, 2021). "Liver‐specific Atg7 deletion predisposes mice to liver tumorigenesis, although these tumours were not reported to become malignant." (PMID 34725936, 2021). "ATG7 is an essential regulator of autophagy, a process involved in tumor suppression, maintenance of the stemness properties of cancer cells, disease recurrence, and anticancer drug resistance, and ATG7 upregulation in recipient cells induces resistance to erlotinib." (PMID 33920605, 2021). "Recently, it has been shown that the loss of Atg7 leads to a stress response only in tumor but not in non-transformed intestinal epithelial cells, potentially opening up a therapeutic window in the context of CRC treatment." (PMID 32046105, 2020). "Moreover, the inhibitory role of m-THPC-PDT on tumor volume was relieved by the knockdown of ATG7 in vivo." (PMID 33130826, 2020). "Regressed tumor growth was observed in a xenograft nude mouse model after transplantation of FoxO1-expressing cancer cells but not after transplantation of FoxO1-expressing cancer cells upon a stable knockdown of Atg7, demonstrating that FoxO1 exerts tumor-suppressor activity by inducing ACD43." (PMID 32591647, 2020). "Moreover, the deletion of Atg5 or Atg7, atg13 or Ulk1, Fip200, and Atg7 decrease tumor progression in various oncogene-driven cancer types." (PMID 33260729, 2020). "This tumour-suppressive role of autophagy is supported by early studies that showed increased development of spontaneous, potentially benign, lung and liver tumours and lymphomas in mice deleted of autophagy genes Beclin 1, Atg7 and Atg5." (PMID 32873152, 2020). "When both alleles of Pten were deleted, autophagy‐deficient tumours were formed; however, loss of Atg7 did not accelerate tumour onset." (PMID 32745353, 2020). "Consequently, autophagy inhibition, following ATG5 or ATG7 deletion, leads to chronic oxidative stress, accumulation of damaged mitochondria, tissue damage and inflammation which all favor tumor initiation." (PMID 29783720, 2018). "Furthermore, HULC overexpression in vivo induced tumor formation, and reduced ATG7, LC3 expression, while inducing SQSTM1 expression; however, we found that HULC overexpression did not influence ATG5, ATG12, Beclin-1, VPS34, P150 or UVRAG expression." (PMID 29022892, 2017). "In this study, following our identification of the core autophagy regulator Atg8a/GABARAP, Atg7 and Atg9 in a large-scale screen for RasV12-cooperating tumour suppressors in Drosophila, we investigate the tumour-suppressive role of autophagy in Ras-activated tissues." (PMID 28581519, 2017). "Tumor suppressive roles for autophagy were demonstrated in mice with Becn1/Beclin-1 heterozygosity, systemic mosaic Atg5 deletion or liver-specific deletion of Atg7." (PMID 26956429, 2016).
tumor (continued). "During oncogenesis in genetically engineered mice, reduced hemizygous expression of genes required for autophagy (BECN1, Atg4, ATG5, Atg7) can accelerate spontaneous or chemically induced tumor formation, suggesting that autophagy can serve as a tumor suppressor." (PMID 26247722, 2015). "In a model of KRas-dependent NSCLC, the inhibition of autophagy through inducible Atg7 deletion leads to abnormal accumulation of mitochondria and decreases in proliferation and necrotic cell death, which in combination translated into reduced tumor burden." (PMID 25328887, 2014). "Given their altered metabolism and increased cellular dysfunction, it might have been predicted that tumor cells would be critically dependent on ATG7 and autophagy for homeostasis and survival." (PMID 24599075, 2014). "Therefore, we investigated whether MHC-I is involved in a putative mechanism of ATG7-mediated tumor immune evasion." (PMID 38627815, 2024). "Consistently, the activation of the Akt/mTOR pathway decreased with ALO treatment in NSCLC cells in vitro and mouse tumor models in vivo, whereas the levels of Beclin‐1 and ATG7 increased, indicating that ALO may promote autophagosome formation by interfering with the Akt/mTOR pathway." (PMID 39166458, 2024). "In mouse tumors generated by chemical treatment, there was no significant change resulting from the deletion of Atg7, but the deletion of Atg7 in tumors caused by HRas mutation markedly suppressed tumor progression based on the size of the tumor and the survival rate of the mice." (PMID 38067169, 2023). "Interestingly, ATG7 conditional knockout mice developed multiple tumors in the liver, and additional knockdown of the autophagy receptor protein p62 reversed this phenotype, suggesting that p62 accumulation due to autophagy inhibition promotes tumor formation." (PMID 36814341, 2023). "The absence of Atg7 from epithelial cells was associated with lower tumor numbers per mouse in response to chemical carcinogenesis and with reduced tumor size and lower mortality in carcinogenesis driven by the activation of Ras-dependent signaling through transgenic SOS." (PMID 36429119, 2022). "Tumor-associated myeloid cells exhibited higher transcriptional expression of molecules linked to the “find me” (G2A), “eat me” (CD93, TIM1, SCARF1, SLC2A1, GAS6, TREM2, AXL, C1QA), and downstream processing (NR1H3, ATG7, PPARG, ABCA1, PPARD, DOCK180) phases of efferocytosis." (PMID 36439171, 2022). "Together, these data support a context‐specific role of ATG7 in carcinogenesis (perhaps driven by genetic and environmental cues including microbial exposure) and highlight that the relationship between autophagy and tumour formation and progression are even more complex that initially thought." (PMID 34725936, 2021). "Recent studies on the tumor and brain injury suggested that ATG7 could be modulated by miR-96." (PMID 34306061, 2021). "In addition, in the BGC-823 cell-mediated xenograft model, immunohistochemical staining showed increased LC3-II and ATG7 expression together with decreased SQSTM1 expression in the tumor tissues of the apatinib group compared with the expression in the tumor tissues of the control vehicle group." (PMID 32139670, 2020). "However, the inhibitory effect of m-THPC-PDT on tumor volume was relieved by the knockdown of ATG7." (PMID 33130826, 2020). "On the other hand, autophagy may protect tumor cells by providing extra arginine in the microenvironment of a liver-specific Atg7 or Atg5 deletion mice model, thereby indicating that autophagy partially compensates for nutrient loss in such condition and thus promotes cell growth." (PMID 33260729, 2020). "Moreover, for the first time, we discovered that ATG7‐mediated autophagy plays a crucial role for human BC invasion in vitro and in xenograft tumor growth in vivo, which provides significant insight into understanding ATG7‐mediated autophagy in bladder carcinogenesis and progression." (PMID 31016112, 2019).